MIR135A2 (microRNA 135a-2)
Synonyms: hsa-mir-135-2; hsa-mir-135a-2; MIRN135-2; MIRN135A2; mir-135a-2
Gene: MicroRNA gene on chromosome 12 (97,563,812 to 97,563,911, forward strand). Ensembl gene ENSG00000207586.
Gene Ontology:
Biological process: miRNA-mediated post-transcriptional gene silencing
Cellular component: RISC complex
Homologues: Orthologues: chimpanzee ptr-mir-135a-2 (100% identical), dog MIR135A2 (100% identical), guinea pig MIR135A2 (100% identical), macaque mml-mir-135a-2 (100% identical), pig ssc-mir-135-2 (100% identical), rabbit MIR135A2 (100% identical), mouse Mir135a-2 (98% identical), tropical clawed frog xtr-mir-135-1 (95% identical), zebrafish dre-mir-135a (66% identical). Paralogues in human: MIR135B (60% identical), MIR135A1 (59% identical).